ROCK2 (Rho associated coiled-coil containing protein kinase 2)
Diseases named in the same sentence as ROCK2 in open-access papers (continued):
Sharing a sentence is not in itself a finding about the gene and the disease.
brain injury (2 papers, 2022 to 2025). Acute and chronic (see also brain INJURIES, CHRONIC) injuries to the brain, including the cerebral hemispheres, CEREBELLUM, and brain STEM. "Their findings showed that miR-335 prevented apoptosis and enhanced SG formation in AIS via lowering ROCK2 expression, suggesting that it could be a therapeutic target for brain injury." (PMID 36250025, 2022).
ciliopathies (2 papers, 2025). "Specific ROCK2 ablation or inhibition has a broad effect in rescuing ciliary function over several ciliopathy disease classes." (PMID 40253509, 2025). "We propose that ROCK2 inhibition represents a novel, disease-modifying therapeutic approach for heterogeneous ciliopathies, including PKD." (PMID 40253509, 2025). "We propose that ROCK2 inhibition represents a novel, disease-modifying therapeutic approach for heterogeneous ciliopathies." (PMID 40253509, 2025). "Repurposing ROCK2 is a viable treatment for ciliopathies, for which a limited therapeutic option is available." (PMID 40253509, 2025). "Fasudil hydrochloride is a selective potent ROCK2 inhibitor, which was reported to rescue cilia formation after knockdown of several known ciliopathy genes in different cellular disease models." (PMID 39934925, 2025). "In conclusion, our work suggests that ROCK2 is a key mediator of cilium formation and function and determines that ROCK2 inhibition has a broad effect in rescuing ciliogenesis and ciliary function over several ciliopathy disease classes." (PMID 40253509, 2025). "We next assessed if ROCK2 inhibition could have potential therapeutic benefit for the most common ciliopathy, autosomal dominant polycystic kidney disease (PKD)." (PMID 40253509, 2025). "In this study, two hypothesis-free approaches highlight ROCK2 as a potential therapeutic target for the restoration of cilia in ciliopathy patients." (PMID 40253509, 2025). "Since the newer, more selective ROCK2 inhibitors may be more promising alternatives for ciliopathy disease indications, future work should focus on preclinical studies of belumosudil or related isoquinolone derivatives as potential candidates for drug repurposing." (PMID 40253509, 2025).
Cirrhosis (2 papers, 2017 to 2022). A chronic disorder of the liver in which liver tissue becomes scarred and is partially replaced by regenerative nodules and fibrotic tissue resulting in loss of liver function. "Despite these limitations our data comprehensively demonstrate that in cirrhosis, multiple adaptations are responsible for reduced vascular tone, and targeting only one component such as enhancing Ca2+ influx, or modulating ROCK2 expression may not be sufficient to reverse them." (PMID 28430609, 2017).
coronary artery disease (2 papers, 2013 to 2023). "Association of ROCK2 with the severity of coronary artery disease." (PMID 23326532, 2013).
cyst (2 papers, 2013 to 2025). A sac-like closed membranous structure that may be empty or contain fluid or amorphous material. "ROCK inhibitors, including one selective for ROCK2, restored renal tubule formation whilst reducing cyst formation in a cystogenic mIMCD3 Pkd1−/− 3D kidney model." (PMID 40253509, 2025).
diabetic cardiomyopathy (2 papers, 2014 to 2020). Diabetic cardiomyopathy is a disorder of the heart muscle in people with diabetes. "Overall, this study establishes that ROCK2 as a critical node in the development of diabetic cardiomyopathy and an important target for its treatment, as it’s inhibition will simultaneously improve multiple signaling pathways in the diabetic heart." (PMID 24466133, 2014). "This study demonstrates that over-activation of ROCK2 contributes to diabetic cardiomyopathy by multiple mechanisms, including direct phosphorylation and activation of PKCβ2 and interference with the PDK-1-mediated phosphorylation and activation of AKT and translocation of GLUT4." (PMID 24466133, 2014).
graft versus host disease (2 papers, 2020 to 2024). An immune system disorder that occurs after allogeneic hematopoietic stem cell transplant and is a reaction of donor immune cells against host tissues. "Belumosudil (BEL) is a specific inhibitor of Rho-associated coiled-coil kinase 2 (ROCK2), which has shown great potential as a therapy for inflammatory and autoimmune illnesses, including graft-versus-host disease (GVHD)." (PMID 39391480, 2024). "Since this drug is used in clinical trials for patients with graft versus host disease (GVHD) and psoriasis, ROCK2 inhibitors may could be used to treat DKD." (PMID 33101039, 2020).
inflammatory bowel disease (2 papers, 2020 to 2025). A spectrum of small and large bowel inflammatory diseases of unknown etiology. "Previous reports showed that ROCK2 was activated in lung endothelial cells during inflammation, and the level of ROCK2 was significantly up-regulated in the inflamed mucosa from the patients with inflammatory bowel disease." (PMID 32684089, 2020).
ischemia (2 papers, 2022 to 2025). A hypoperfusion of the BLOOD through an organ or tissue caused by a PATHOLOGIC CONSTRICTION or obstruction of its BLOOD VESSELS, or an absence of BLOOD CIRCULATION. "Furthermore, AAV-sh.ROCK2 increased neuronal survival and promoted neurogenesis following middle cerebral artery occlusion surgery as well as long-term motor functional recovery after ischemia/reperfusion injury." (PMID 40537020, 2025).
kidney damage (2 papers, 2024 to 2025). "In cardiovascular and metabolic diseases, isoform-specific targeting of ROCK1 or ROCK2 holds promise for improving endothelial function, attenuating fibrosis, and protecting against diabetic complications such as cardiomyopathy and nephropathy." (PMID 41377066, 2025). "To begin testing for functional links between ROCK2 expression and ADR-induced kidney damage, we crossed Rock2-flox mice with mice expressing Cre recombinase under the control of the Nphs2/Podocin promoter to generate mice with podocyte-specific disruption of ROCK2." (PMID 38565675, 2024). "Furthermore, genetic and pharmacological inhibition of ROCK2 significantly attenuated albuminuria and histological abnormalities in ADR-induced nephropathy." (PMID 38565675, 2024).
Myocardial fibrosis (2 papers, 2021 to 2024). "Following these findings, we assumed that MFA attenuated proliferation and migration ability of HCFs and thus attenuated myocardial fibrosis by suppressing the pRB-E2F1/CCNE2 and the RhoA/ROCK2 pathway." (PMID 34483923, 2021). "With these findings, we concluded that MFA suppressed proliferation and migration ability of HCFs and hence attenuated myocardial fibrosis, the mechanism of that was by suppressing the RB-E2F1/CCNE2 and the RhoA/ROCK2 pathway." (PMID 34483923, 2021).
pleural mesothelioma (2 papers, 2017 to 2020). A neoplasm that arises from the mesothelial cells of the pleura. "To gain insights into the mechanisms underlying elevated YAP activity in pleural mesothelioma, we examined YAP, ROCK1 and ROCK2 expression levels in mesothelioma tissue samples from 60 patients using immunohistochemistry." (PMID 28470935, 2017).
renal carcinoma (2 papers, 2017). A carcinoma arising from the epithelium of the renal parenchyma or the renal pelvis. "In both bladder and renal cancers, an elevation of ROCK2 expression has been associated with tumor invasion, metastasis, and an unfavorable prognosis." (PMID 28554330, 2017). "In contrast, anti-ROCK2 showed only weak staining in normal glomerular Bowman’s epithelium and proximal tubule epithelium whereas no reactivity was evident in kidney carcinoma." (PMID 28554330, 2017). "In support of this, ROCK2 autoantibodies were not identified in the sera of any of the 37 control patients with bladder or renal carcinoma." (PMID 28554330, 2017).
retinopathy of prematurity (2 papers, 2019 to 2020). A bilateral retinopathy characterized by neovascularization, scarring, retinal detachment, and eventually blindness. "Specifically, inhibition of JNK alone and in combination with ROCK2 were, respectively, identified for delaying preterm labor and mitigating retinopathy of prematurity." (PMID 30815434, 2019). "Capacity to reduce vaso-obliteration and microglial activation, hallmarks of retinopathy of prematurity, was exhibited in the OIR model by peptides (e.g., 2d, 2l, 2n, and 2q), which had demonstrated ROCK2 inhibitory activity." (PMID 33415098, 2020).
sickle cell disease (2 papers, 2022 to 2025). Sickle cell anemias are chronic hemolytic diseases that may induce three types of acute accidents: severe anemia, severe bacterial infections, and ischemic vasoocclusive accidents (VOA) caused by sickle-shaped red blood cells obstructing small blood vessels and capillaries. "In transgenic mice, for sickle cell disease, Rho signaling is aberrant, particularly for the Rock2 expression, which contributes to the pathophysiology of priapism." (PMID 36313553, 2022).
subarachnoid hemorrhage (2 papers, 2020 to 2024). A serious neurological disorder characterized by intracranial hemorrhage into the subarachnoid space. "Fasudil hydrochloride, a ROCK2 inhibitor, has been used clinically to improve cerebral vasospasm after subarachnoid hemorrhage." (PMID 38825816, 2024). "Moreover, ROCK2 inhibition can promote autophagy and reduce hippocampal damage during subarachnoid hemorrhage (SAH)." (PMID 33153478, 2020).
acid reflux (1 paper, 2016). "It is possible that persistent acid reflux present in BE patients may increase intracellular calcium, activate ROCK2 and thereby upregulate NOX5-S." (PMID 26901778, 2016).
acute lymphoblastic leukemia (1 paper, 2022). Leukemia with an acute onset, characterized by the presence of lymphoblasts in the bone marrow and the peripheral blood. "Rho‐associated protein kinase 2 (ROCK2) is an important therapeutic target, and its upregulation was confirmed in many cancers, including T‐cell acute lymphoblastic leukemia (T‐ALL)." (PMID 35715800, 2022).
Ataxia (1 paper, 2017). Ataxia refers to impaired coordination of voluntary muscle movement. "Activation of ROCK2 has been implicated in several adult-onset neurodegenerative conditions where synaptic pathology is present, such as HD, AD, ataxia, and in Purkinje cell degeneration." (PMID 28963550, 2017).
autoimmune encephalitis (1 paper, 2017). Inflammation of the brain secondary to an immune response triggered by the body itself. "ROCK2 is not the only intracellular kinase targeted by antibodies in autoimmune encephalitis." (PMID 28554330, 2017).
autosomal recessive hearing loss (1 paper, 2025). "Mutations inPJVK cause autosomal recessive hearing loss (DFNB59), and Pejvakin modulates actin dynamics to sustain OHC activity and survival in a cell-autonomous manner, which may depend on its interaction with ROCK2 and other Rho effectors." (PMID 40391522, 2025).
bladder tumor (1 paper, 2017). "ROCK2 was expressed in affected brain tissue and archival bladder tumor samples of this patient." (PMID 28554330, 2017).
cervical squamous cell carcinoma (1 paper, 2020). A squamous cell carcinoma arising from the cervical epithelium.
chronic lymphocytic leukemia (1 paper, 2015). "The majority of previous studies investigating AMFR and ROCK2 have focused on solid tumors, and only one demonstrated that the expression of AMFR was associated with progression in chronic lymphocytic leukemia." (PMID 26136223, 2015). "The expression of AMFR and ROCK2 are reported to correlate with tumor stage and survival rates in types of solid cancer, and the expression of AMFR is reported to be associated with progression in chronic lymphocytic leukemia." (PMID 26136223, 2015).
corticobasal degeneration (1 paper, 2025). "Elevated levels of insoluble Tau are associated with increased ROCK1 and ROCK2 protein levels in supranuclear palsy (PSP) and corticobasal degeneration (CBD)." (PMID 39851517, 2025).
COVID-19 (1 paper, 2025). A disease caused by infection with severe acute respiratory syndrome coronavirus 2. "TDI01 is a novel and highly selective ROCK2 inhibitor, which provides a potential valuable candidate for the treatment of ALI/ARDS due to COVID-19." (PMID 40103594, 2025).
cystic kidney disease (1 paper, 2025). A congenital or acquired kidney disorder characterized by the presence of renal cysts. "Our results indicate that specific ROCK2 inhibitors (e.g. belumosudil) could be repurposed for cystic kidney disease treatment." (PMID 40253509, 2025).
cystitis (1 paper, 2017). Inflammation of the urinary bladder. "Expression of ROCK1 and ROCK2 at the mRNA level was also increased in the bladder of rats in the model of HCl-induced cystitis." (PMID 28220212, 2017).
cytomegalovirus infection (1 paper, 2025). A herpesvirus infection caused by Cytomegalovirus. "Rock2, Ccl5, Plk1, Rel, and Ctnnb1 are mainly associated with inflammatory responses, including positive regulation of IκB kinase/NF-κB signalling and human cytomegalovirus infection." (PMID 41007634, 2025).
endometrial cancer (1 paper, 2025). Primary or metastatic malignant neoplasm involving the endometrium (mucous membrane that lines the endometrial cavity). "And through the correlation analysis of the expressions of ECT2 and RhoA, ROCK1, and ROCK2 in endometrial cancer samples in TCGA database, it was found that the expression of ECT2 was significantly positively correlated with RHOA, ROCK1, and ROCK2." (PMID 40655948, 2025).
escherichia coli infection (1 paper, 2021). Infection with the organism Escherichia Coli. "In the studied MS patients, increased CSF nucleolin expression and SNP associations on WASL and ROCK2 genes were detected, all of which are components of the Pathogenic Escherichia coli infection pathway." (PMID 39544199, 2021).
esophageal squamous cell carcinoma (1 paper, 2015). Esophageal squamous cell carcinoma (ESCC) is a type of esophageal carcinoma (EC) that can affect any part of the esophagus, but is usually located in the upper or middle third. "The inhibition of the expression of ROCK2 by AMFR has been previously observed in esophageal squamous cell cancer cells, indicating that AMFR may affect the expression of ROCK2." (PMID 26136223, 2015).
Glomerular sclerosis (1 paper, 2024). Accumulation of scar tissue within the glomerulus. "In addition, we performed pharmacological intervention for ROCK2 to demonstrate protection against podocyte loss and glomerulosclerosis in ADR-injected mice." (PMID 38565675, 2024). "We have now provided proof of concept that ROCK2 inhibition attenuated glomerular sclerosis, GBM abnormalities, and subsequent tubulointerstitial fibrosis." (PMID 38565675, 2024). "Conditional knockout mice in which the ROCK2 gene was selectively disrupted in podocytes (PR2KO) were resistant to albuminuria, glomerular sclerosis, and podocyte damage induced by ADR injection." (PMID 38565675, 2024). "ROCK2 is upregulated in ADR-induced glomerular injury, a rodent model of FSGS characterized by podocyte damage followed by glomerulosclerosis, tubulointerstitial inflammation, and fibrosis." (PMID 38565675, 2024). "In contrast to WT mice, those lacking ROCK2 exclusively in podocytes were completely impervious to glomerular sclerosis." (PMID 38565675, 2024).
hypogonadism (1 paper, 2021). A disorder characterized by decreased function of the gonads. "In this study, we investigated effects of testosterone undecanoate therapy on the ROCK-2 expression and bladder behavior in the rat BOO and hypogonadism models." (PMID 33387987, 2021). "We suggest that, in hypogonadism, testosterone treatment has a substantial influence on BOO-induced detrusor overactivity without significantly change in ROCK-2 upregulation." (PMID 33387987, 2021).
hypophosphatemia (1 paper, 2025). Lower than normal levels of phosphates in the circulating blood. "Ruxolitinib, a Janus kinase 1/2 inhibitor (5 mg twice daily), led to multiple hospitalizations for systemic infections, including near-lethal pneumonia, and belumosudil, a rho-associated coiled-coil-containing protein kinase 2 (ROCK-2) pathway inhibitor (200 mg/day), caused severe hypophosphatemia." (PMID 40565814, 2025).
intestinal cancer (1 paper, 2013). "ROCK-2 has been localized to invadopodia in intestinal cancer cells and siRNA-mediated knock-down of ROCK reduced MMP-2 activity and invasion." (PMID 23940598, 2013).
keloid (1 paper, 2025). An irregularly shaped, elevated mark on the skin caused by deposits of excessive amounts of collagen during wound healing. "We then compared the expression of RhoA and ROCK2 in fibroblasts from 10 normal skin samples, 10 hypertrophic scars, and 10 keloids by qPCR and western blot." (PMID 39781462, 2025).
Left atrial enlargement (1 paper, 2015). Increase in size of the left atrium. "The results of this study indicated that inhibition of ROCK2 may be potential candidate target to prevent left atrial contractile dysfunction and left atrial enlargement in patients with MR." (PMID 25956928, 2015).
macular degeneration (1 paper, 2024). Loss of vision in the central portion of the retina (macula), secondary to retinal degeneration. "Aging increased Rho-associated coiled-coil-containing protein kinase 2 (ROCK2) signaling, promoting the expression of proangiogenic M2-like macular-degeneration-associated macrophages." (PMID 38770313, 2024).
malignant vascular tumors (1 paper, 2017). "Collectively, these data indicate that ROCK proteins are overexpressed in diverse vascular tumors and suggest that specific targeting of ROCK2 proteins may show efficacy against malignant vascular tumors." (PMID 28709411, 2017).